FUS (FUS RNA binding protein)
Diseases named in the same sentence as FUS in open-access papers (continued):
Sharing a sentence is not in itself a finding about the gene and the disease.
neurodegenerative disease (continued). "FUS is an RNA-binding protein involved in familiar forms of ALS and FTLD that also assembles into fibrillar cytoplasmic aggregates in some neurodegenerative diseases without genetic causes." (PMID 37179431, 2023). "HTT, neurofilament heavy chain (NF‐H), Tau (MAPT), FUS, TDP‐43, HNRNPA1, HNRNPD, RPL7 and actin (ACTB, found aggregated in Hirano bodies in several neurodegenerative diseases; Hirano, 1994), were selectively aggregated upon RNase A/T1 treatment of human neuronal lysates." (PMID 32945072, 2020). "An increased duration of TDP-43 and FUS within the cytoplasm after stress may render the environment more aggregation-prone, which may be poorly tolerated in the context of ALS and related neurodegenerative diseases." (PMID 33172210, 2020). "Likewise, small changes in the primary sequence of Hsp104 yield potentiated protein disaggregases that reverse the aggregation and buffer toxicity of various neurodegenerative disease proteins, including α-synuclein, TDP-43, and FUS." (PMID 27014702, 2016). "Does mutant FUS misfold as we have seen for other ALS and neurodegenerative disease proteins?" (PMID 25289647, 2014). "Thus, RNA targets of both FUS and TDP-43 emphasize that alterations in RNA processing pathways play a central role in neurodegenerative diseases." (PMID 23577159, 2013). "Intracellular accumulations of wild type TDP-43 and FUS are observed in a growing number of late-onset diseases suggesting that TDP-43 and FUS proteinopathies may contribute to multiple neurodegenerative diseases." (PMID 22363618, 2012). "Furthermore, 306C7B3 binding was specific to α-synuclein deposits with no immunoreactivity observed to other amyloid deposits characteristic of neurodegenerative diseases such as TDP-43 inclusions in FTLD-TDP and ALS, FUS inclusions in FTLD-FET, tau pathology in PSP and AD, as well as Abeta in AD." (PMID 37322068, 2023).
tumor (91 papers, 2008 to 2026). "To gain further insight into the behavior of these tumors, we analyzed a spectrum of EWSR1/FUS::NFATC2-rearranged neoplasms and discuss their radiologic, diagnostic, and molecular features in relation to their prognosis." (PMID 36555836, 2022). "To gain further insights into the behavior of these tumors, we analyzed a spectrum of EWSR1/FUS::NFATC2-rearranged neoplasms and discuss their key diagnostic and molecular features in relation to their prognosis." (PMID 36555836, 2022). "Similarly, John R. Goldblum and colleagues reported a high frequency (9/11) of ALK positivity in AFH, which is an EWSR1 (or rarely FUS) rearrangement-associated neoplasm characterized by accompanying lymphoplasmacytic infiltrate." (PMID 37120571, 2023). "Neoplasms with fusions between Ewing sarcoma breakpoint region 1 (EWSR1) or fused in sarcoma (FUS) genes and genes encoding the CREB family of transcription factors (ATF1, CREB1, and cAMP-responsive element modulator [CREM]) are one such tumor type." (PMID 40242428, 2025). "By isolating tumor-infiltrating T cells, we found that the FUS and TAF15 group showed an increased number of tumor-infiltrating T cells, although the T cell numbers in blood were comparable across the control, FUS and TAF15 groups." (PMID 41023404, 2025). "Synthetic ZFTA fusion oncoproteins utilizing IDRs from EWS and FUS restored condensate formation, oncogene transcription and tumour initiation in mice." (PMID 40866513, 2025). "With the widespread use of RNA sequencing technology, the EWSR1/FUS::CREB fusion mesenchymal tumor family has expanded rapidly to include potentially aggressive tumors rather than any well-established WHO entity." (PMID 41341384, 2025). "First, besides promoting the expression of SCD1 which is the downstream effector for anti‐ferroptosis, LXRα also upregulated the levels of miR‐181a‐5p and its RNA‐binding protein FUS, thereby enhancing the enrichment of miR‐181a‐5p in tumor‐released EVs." (PMID 38031260, 2024). "RT‐qPCR and representative Western blots of the specimens showed that FUS mRNA and protein were upregulated in the tumour tissue." (PMID 38682349, 2024). "Immunofluorescence and immunohistochemistry assays showed that exosomes promoted the expression of HSPB1, FUS and ki‐67 in tumour tissues, and knockdown of HSPB1 reversed the effects of exosomes." (PMID 38682349, 2024). "A distinct feature of our series is the examination of the tumor samples, not only for histological diagnosis but also for the presence of the pathognomonic gene translocation FUS::DDIT3 or EWSR1::DDIT3." (PMID 36907960, 2023). "TATA-box-binding protein-associated Factor 15 (TAF15), a member of the FUS/EWS/TAF15 (FET) family, contributes to the progression of various tumours." (PMID 37037864, 2023). "The EWSR1/FUS-CREB fusion family of neoplasms have been ever expanding to encompass a variety of histologically, immunophenotypically, biologically, and topographically distinct entities." (PMID 37097347, 2023). "Accordingly, EWSR1/FUS::CREB fusion neoplasms are not well known in the female genital tract pathology literature and are, hence, possibly under-recognized." (PMID 37097347, 2023). "In our study, we analyzed a biological spectrum of bone and soft tissue EWSR1/FUS::NFATC2-rearranged neoplasms." (PMID 36555836, 2022). "Immunohistochemistry with CD99 and EMA plays a limited role, as both benign and malignant EWSR1/FUS::NFATC2-rearranged neoplasms can stain positive." (PMID 36555836, 2022). "Our study supports and expands previously reported molecular findings of EWSR1/FUS::NFATC2-rearranged neoplasms." (PMID 36555836, 2022). "This means that the percentage of positive cells is below the cutoff of 15% (10–12% for EWSR1) or that 0% positive tumor cells were detected (for FUS, CIC, and BCOR)." (PMID 36232302, 2022). "Among 28 EWS/FUS-ETS variants reported so far, we detected five using cell lines and tumor tissues, and additionally, we identified a novel variant." (PMID 34749732, 2021).
tumor (continued). "Five neoplasms had different gene fusions including a neoplasm with FUS-CREM gene fusion, two SS with SS18- SSX gene fusion, two ASPS with TFE3-ASPSCR1 gene fusion, and one SFT with immunolabeling for STAT6 indicating a STAT6-NAB2 gene fusion (for details)." (PMID 34350470, 2021). "Given the well-known role played by FUS protein in tumorigenesis and the control of tumor cells growth, we set out to investigate its role in the control of NSPC properties." (PMID 34299185, 2021). "Diffuse membranous CD99 immunoreactivity is a hallmark of this tumor and more than 90% of tumors were reported to have EWSR1/FUS-ETS." (PMID 34749732, 2021). "Meanwhile, the expression of FUS protein in CRC tumor tissue was significantly increased than that in paired para-tumor tissues." (PMID 32188489, 2020). "Compared to the control group, the sh‐BACH2, sh‐FUS, TSLNC8‐OE and sh‐BACH2+sh‐FUS+TSLNC8‐OE groups produced smaller tumour volumes." (PMID 32892482, 2020). "Our mouse models showed that specific tissues and developmental stages are permissive for FUS-CHOP-driven tumor formation." (PMID 31427882, 2019). "In corroboration with previous reports, we find that circFndc3b interacts with FUS, an RNA binding protein that acts as a tumor suppressor gene in many human cancers." (PMID 31541092, 2019). "FUS belongs to the FET family and it encodes a multifunctional RNA-binding protein which is highly associated with tumor progression." (PMID 27764782, 2016). "We found that the oncogene FUS was present in a high-level narrow amplification at 16p11.2 in one tumor (37818)." (PMID 21151896, 2010). "Furthermore, the fusion of the CREB gene family with EWSR1 or FUS gene partners leads to a wide variety of tumor pathogenesis." (PMID 41341384, 2025). "LGFMS and SEF may appear together as a hybrid tumor, and they share diagnostic features including MUC4 immunoreactivity and FUS gene rearrangements." (PMID 38254244, 2024). "On the other hand, we found that LXRα could also activate the transcription of miR‐181a‐5p and FUS, resulting in an enrichment of miR‐181a‐5p into tumor‐derived EVs." (PMID 38031260, 2024). "Whether these gonadal neoplasms are part of the EWSR1/FUS::ATF1/CREM fusion-driven tumor spectrum with subtle organ-specific phenotypic differences remains controversial." (PMID 39031200, 2024). "Furthermore, LXRα activates the transcription of both miR‐181a‐5p and its binding protein FUS to increase the recruitment of miR‐181a‐5p in tumor‐derived extracellular vesicles (EVs)." (PMID 38031260, 2024). "Recently, a group of intra-abdominal FET(EWSR1/FUS)::CREB(CREM/ATF1) fused unclassified neoplasms has been reported followed by recent recognition of an analogous extra-abdominal category of unclassified neoplasms carrying EWSR1::ATF1 fusions." (PMID 39249507, 2024). "Considering FUS–circTBC1D14 SG formation, we assumed that circTBC1D14 might contribute to its tumor progression function through the granules under hypoxic conditions, among which HIF‐1α is an essential element." (PMID 36806670, 2023). "Furthermore, disruption of IDR in LEF1 abolishes its capacity to promote tumor proliferation and metastasis, whereas substitution with FUS IDR reinstates this promoting activity." (PMID 37657935, 2023). "It is conceivable that the EWSR1/FUS::NFATC2 fusion might be a very early event in tumor initiation, and additional events are required for progression." (PMID 36555836, 2022). "These tumours consistently have either FUS::CREB3L28 or FUS::CREB3L19 gene fusions." (PMID 35484289, 2022). "Moreover, the expression of circLONP2 was positively correlated to the mRNA level of FUS in primary CRC tumor tissues (n = 110), and FUS mRNA expression was significantly correlated with clinicopathological characteristics." (PMID 32188489, 2020).
tumor (continued). "Interestingly, in L108 it was also possible to see the subclonality of this event: while the SRF rearrangement was observed only in a subpopulation of the cells, FUS rearrangement was observed in almost all tumor cells (92%)." (PMID 28947952, 2017). "When this miRNAs is overexpressed in cancer cell lines, SUFU (suppressor of fused) and FUS-1 (FUS RNA binding protein), two tumour suppressor genes, are downregulated, and as a consequence there is an increase in the levels of VEGF, thus increasing cell survival and reducing cell death." (PMID 25197665, 2014). "The observation that both domains of FUS-DDIT3 are required to regulate eIF4E expression provides the first molecular evidence that the FUS component of the fusion protein is required not only for transformation but also influences the phenotype of the tumor cells." (PMID 18596980, 2008). "Fusions between members of the FET gene family (EWSR1 and FUS) and genes encoding for the CREB-transcription factor family (ATF, CREB1, and CREM) have been reported in a variety of clinically and pathologically distinct neoplasms of mesenchymal, epithelial and mesothelial origin." (PMID 39031200, 2024). "However, neoplasms harboring EWSR1-CREM/FUS-CREM fusions are rare and poorly characterized." (PMID 34228212, 2022). "Furthermore, altered FUS levels modulate cell proliferation in various tumor cells." (PMID 34299185, 2021). "However, FUS’ role in cancer cells remains puzzling and clearly dependent on the tumor origin." (PMID 34299185, 2021). "By scaffolding FUS to stabilize GPX4 mRNA, lncRNA-PRLB maintains GPX4 expression and enables tumor cells to evade ferroptotic cell death." (PMID 41783067, 2026). "The downregulation of FUS in the GH3 and MMQ cell lines resulted in a significant reduction in tumor volume." (PMID 41510173, 2026). "We assessed for potential differences in patient and tumor characteristics and outcomes based on the fusion partner (e.g., EWSR1 or FUS)." (PMID 40361368, 2025). "Despite the disparity in sample sizes within the HPA database, which includes 10 normal samples and 100 tumor samples, we identified HNRNPH1, FUS, and HNRNPU as proteins that are highly expressed in GBM." (PMID 40340965, 2025). "RNA-seq profiling of ZR-sub-FUS:IDR and ZR-sub-EWS:IDR tumours revealed activation of ZR signature transcriptional programs." (PMID 40866513, 2025). "During the new trial, we observed that FUS and TAF15 slowed tumor progression, which is consistent with the result from previous experiments." (PMID 41023404, 2025). "We found that FUS and TAF15 CAR-T inhibited tumor growth better than the control CAR-T, which is consistent with the in vitro killing results." (PMID 41023404, 2025). "Hence, the exact molecular mechanism of FUS::DDIT3 in tumor cell transformation remains unclear." (PMID 38671504, 2024). "Fused in sarcoma (FUS) is a classical regulator involved in DNA replication, translation, and repair, which plays a critical role in cell proliferation and tumor progression." (PMID 39550559, 2024). "In addition, FUS–circTBC1D14 SGs can initiate a cascade of SG‐linked proteins to recognize and control the elimination of SGs by recruiting LAMP1 and enhancing lysosome‐associated autophagy flux, thus contributing to the maintenance of cellular homeostasis and promoting tumor progression in TNBC." (PMID 36806670, 2023). "In the last decade, new tumor entities have been described, including EWSR1/FUS::NFATC2-rearranged neoplasms of different biologic behavior." (PMID 36555836, 2022). "Respondents were mostly unsure of how to classify FUS-ETS gene family fusions and EWSR1 round cell sarcoma with non-ETS partners, which is consistent with their difficulty classifying these tumours and explained by their rare presentation." (PMID 33488267, 2020).
tumor (continued). "However, the most frequent FUS‐ALS mutation R521C was described to impair proper DNA damage response resulting in increased DNA double‐strand breaks evidently found in postmortem human tissue, but none of our 12 R521C patients with partially late disease onset showed evidence for neoplasms." (PMID 31682085, 2019). "In untreated mice the FUS-CHOP chimera was bound to the FN1 promoter in sensitive and resistant tumours." (PMID 31409911, 2019). "The first was a congenital SSRMS tumor in the forearm of a 2-week-old girl with a TEAD1::NCOA2 gene fusion (case 7), and the second was an intraosseous SSRMS in the base of the skull of a 12-year-old boy with a FUS::TFCP2 gene fusion (case 8)." (PMID 40923514, 2025). "Furthermore, 10 of these 26 (38.5%) patients had a tumor with an EWSR1::ATF1 fusion, eight (30.8%) had EWSR1::CREB1 fusion, six (23.1%) had EWSR1::CREM, one (3.8%) had EWSR1::CREB3L3, and one (3.8%) had FUS::CREM fusion." (PMID 38291529, 2024). "The analysis did not detect MDM2 amplification, Rb1 deletion, break apart signals of EWSR1, FUS, DDIT3, or c-myc, or c-myc-IGH fusion signals, but it did detect more c-myc signals in 837 out of 996 tumor cells and 823 out of 1,000 tumor cells." (PMID 36514176, 2022). "The reduction of FUS expression was observed in the tumor xenografts derived from Eca-109 and KYSE-150 cells with GTF2E2 downregulation, and the opposite trend was found in the tumor xenografts derived from TE-1 cells with GTF2E2 upregulation." (PMID 34853466, 2022). "Therefore, eIF4A3 and FUS may constitute key lncRNA-binding proteins that could be part of a pan-cancer molecular mechanism that mediates the tumorigenic properties of most oncogenic lncRNAs and/or generally promotes lncRNA secretion into the systemic circulation from the tumor site." (PMID 35729321, 2022). "FISH analysis of fresh-tissue touch preparations detected EWSR1 split signals in most tumor cells but not FUS split signals." (PMID 34749732, 2021). "ddPCR quantification of translocation events and in vivo detection of translocation suggest that although translocations are forming in mice, not enough cells that are permissive for FUS-CHOP-driven tumorigenesis are edited to form a tumor." (PMID 31427882, 2019). "Instead, when we examined the binding of FUS-CHOP to a target sequence, FN125 by ChIP we found that trabectedin caused the detachment of the chimera only in the sensitive tumour and not in the resistant ML017/ET." (PMID 31409911, 2019). "Preclinical studies indicated that this sensitivity may be associated with trabectedin’s ability to block the activity of FUS-CHOP chimera, allowing the tumor to differentiate into benign lipoblasts." (PMID 28166781, 2017). "Notable RBPs such as FUS (Fused in Sarcoma), YBX2 (Y-box Binding Protein 2), and AUF1 (AU-rich Element RNA-binding Protein 1) could regulate proliferation, migration, and invasion across various tumor cell types." (PMID 40538852, 2025). "This is particularly important in renal cases as rare Xp11-translocation RCC may harbor EWSR1-TFE3 fusions and be indistinguishable from EWSR1/FUS-CREM neoplasms by FISH alone." (PMID 34228212, 2022). "Importantly, although our mouse models identify Prrx1-expressing cells as a source of FUS-CHOP-driven tumors, cells expressing PdgfRα cannot be ruled out as a potential tumor-initiating cell for FUS-CHOP-driven tumors." (PMID 31427882, 2019). "However, EWSR1 and FUS rearrangements were absent in this tumor." (PMID 31915021, 2020). "Next-generation sequencing (NGS) analysis revealed copy number loss of SMARCB1 and a novel GSTT1::IGLC7 fusion in the tumor, while no other gene rearrangements, including those involving EWSR1, NR4A3, or FUS, were detected." (PMID 42052495, 2026).
tumor (continued). "FISH studies demonstrated that the tumor was negative for amplification of MDM2 and rearrangements of EWSR1, FUS, and KMT2A." (PMID 34592995, 2021). "Tumor specimens negative for EWS-specific fusion gene should be analyzed for the panel of known fusion transcripts including CIC-rearrangement, BCOR-rearrangement, EWSR1, or FUS fusion with no-ETS partner." (PMID 36358827, 2022).